MMP13 (matrix metallopeptidase 13)
Diseases named in the same sentence as MMP13 in open-access papers (continued):
Sharing a sentence is not in itself a finding about the gene and the disease.
osteoarthritis (continued). "For example, Sal B dose-dependently suppressed IL-β induced the expression of iNOS, COX-2, MMP-13 and ADAMTS-5 via the inhibition of NF-κB p65 signaling in human osteoarthritis chondrocytes." (PMID 35922815, 2022). "ELISA results demonstrated that exogenous α2MRS significantly inhibited the induction of MMP-13 (p = 0.001), TNF-α (p = 0.005), and IL-6 (p < 0.001) activity in IL-1β-induced human primary osteoarthritis chondrocytes." (PMID 36133821, 2022). "As a result of their ability to inhibit the production of proinflammatory cytokines such as COX-2, NO, MMP-13, and CTX-II while also increasing cartilage thickness, collagen and collagen peptides can be used as an osteoarthritis treatment." (PMID 35866033, 2022). "Osteoarthritis research society international (OARSI) score in cartilage was markedly increased, along with increased MMP‐3, MMP‐13, ADAMTS‐5, ICAM‐1, ERK and p‐ERK expression." (PMID 33939302, 2021). "In conclusion, electroacupuncture for osteoarthritis is accomplished by upregulating the expression of HIF-1α, Sox9, and ACAN and downregulating the expression of MMP13 and ADAMTS5." (PMID 34760015, 2021). "In mice with osteoarthritis (OA), EMF inhibited the expression of inflammatory cytokines, including IL‐1β, ADAMTS4, and MMP13." (PMID 34774092, 2021). "In a mouse model of osteoarthritis, CL82198, an inhibitor of MMP-13, inhibited chondrocyte apoptosis and delayed cartilage degradation." (PMID 34868573, 2021). "In in vitro and in vivo models of osteoarthritis, shikonin inhibited inflammatory responses by reversing the elevated expression of MMP1, MMP3, and MMP13." (PMID 34812264, 2021). "In osteoarthritis (OA), SHED can reduce inflammation, increase the expression of collagen type 2 (COL 2), and decrease the expression of matrix metalloproteinase-13 (MMP-13) and nuclear factor-kB (NF-kB) and thus have the potential to be a treatment of OA." (PMID 34426741, 2021). "A genome-wide analysis of DNA methylation status involving osteoarthritis patients found the MMP3, MMP9, and MMP13 genes to be hypomethylated (with increased gene expression) in osteoarthritis versus non-osteoarthritis chondrocytes." (PMID 33920915, 2021). "MMP-13 is a member of the collagenase group, together with MMP-1 and MMP-8, and is deregulated in different disorders, such as osteoarthritis (OA), rheumatoid arthritis, obesity, and cancer." (PMID 34576138, 2021). "The expression of MMP-13 increased through stimulation by CCL20 and interferon regulatory factor-8 (IRF-8) in chondrocytes derived from patients with osteoarthritis." (PMID 32189997, 2020). "In linking osteoarthritis to metabolic syndrome, the presence of adiponectin positively correlates with the presence of membrane-expressed PGE synthase and MMP-13." (PMID 32116759, 2020). "We analyzed MMP expression to assess the anti-osteoarthritis effects of LI73014F2 and showed that a 50 mg/kg dose of the compound significantly reduced MMP-2, MMP-3, and MMP-13 levels." (PMID 33238379, 2020). "As reported in this recent work, the pre-treatment with RPH had a suppressive effect on the mediators that contributed to the progression of osteoarthritis by inhibiting collagen 2, COX-1-2, MMP-13, TNF-α, and IL-13 expression." (PMID 32340224, 2020). "Other contributions to osteoarthritis from activities related to MMP-3 include MMP-3-mediated activation of MMP-1 and MMP-13." (PMID 32116759, 2020). "The mRNA expression of catabolic factors MMP-3, MMP-7, and MMP-13 was significantly decreased in rat in the FJH-KO100 and FJH-KO150 groups compared with that in rats with MIA induced osteoarthritis (p < 0.05)." (PMID 33233504, 2020). "This prominent microRNA can target osteoarthritis (OA)-related mRNAs, ADAMTS-5, MMP13, COl2a1, and ACAN in human articular chondrocytes." (PMID 31847882, 2019).
osteoarthritis (continued). "In vitro and in vivo studies demonstrated that CJM reduced the IL‐1β‐, IL‐6, IL‐17‐ and TNF‐α‐induced up‐regulation of MMP3, MMP13, ADAMTS4, ADAMTS5 and COX‐2 and blocked osteoarthritis development in a destabilization of the medial meniscus mouse model." (PMID 31148341, 2019). "Previous report has shown that increased MMP-1, MMP-3, MMP-9, MMP-12, and MMP-13, VEGF-A, and COL10A1, triggered by hypoxia-inducible factor (HIF)-2, play a vital role during osteoarthritis development." (PMID 31766662, 2019). "For instance, it has been shown to inhibit the expression of MMP-3, MMP-13, iNOS, and COX-2 on human osteoarthritis (OA) in vivo, thus, making diosgenin a suitable agent for OA therapy." (PMID 29370858, 2018). "In vivo study confirmed that DAS protected the cartilage in the development of osteoarthritis by inhibiting the expression of MMP-1, MMP-3, MMP-13, and IL-1β as well as enhancing the production of collagen II." (PMID 29370858, 2018). "Effects of SAMC on MMP-9, MMP-13, and TIMP-1 protein expression in osteoarthritis chondrocytes were detected using western blot." (PMID 29333456, 2017). "We showed that DJH protected against OVX-induced osteoarthritis by preventing the decrease in articular cartilage, with reduced levels of MMP-3, MMP-13, and also proinflammatory cytokines in OVX rats with osteoarthritis induced by MIA." (PMID 29348767, 2017). "Consistent with previously discussed studies, DDR2 is shown to be a major effector of MMP-13 expression in DMM models, such that almost complete protection from osteoarthritis is shown in DDR2 hypomorphic strains." (PMID 27478294, 2016). "First, Salubrinal downregulates the expression and activity of Matrix Metallopeptidase 13 (MMP13), in chondrocytes, suggesting its potential use for protecting chondrocytes and treating degenerative diseases, such as osteoarthritis." (PMID 27196267, 2016). "Remarkably, inhibition of Hh in explant cultures of human osteoarthritic cartilage samples blocked expression of key genetic markers of osteoarthritis, including the metalloproteinases ADAMTS5 and MMP13, the transcription factor RUNX2, and COL10A131." (PMID 25992955, 2015). "We found that the anti-CD13 blocking antibody AB108310 for murine chondrocytes and SJ1D1 for osteoarthritis human chondrocytes, inhibited the chondrocyte response to recombinant 14-3-3ε by decreasing the expression and release of MMP-3 and MMP-13." (PMID 26208633, 2015). "To address this issue, we focused our attention on the expression levels of molecules that were previously shown to be modulated during the onset of IVD degeneration or osteoarthritis (COL1A1, COL2A1, AGC1, BMP2, MMP13, MGP and P21)." (PMID 21726455, 2011). "An MMP-13-sensitive peptide with thiol groups was incorporated into the hydrogel, enabling on-demand drug release and degradation in response to overexpressed MMP-13 in the osteoarthritis microenvironment, to alleviate disease progression." (PMID 40006582, 2025). "Through the modulation of the SIRT6/NF-KB and Nrf2/NF-KB signaling pathways to activate SIRT6 and downregulate the expression of ADAMTS-4, MMP-13, COX-2, and iNOS, articular chondrocyte degradation is prevented, and the inflammatory response in osteoarthritis (OA) is mitigated." (PMID 39857301, 2025). "Genes related to FAI, DDH, and osteoarthritis include COL1A1, MMP13, and IL-6." (PMID 41019141, 2025). "Chronic circadian rhythm disruption could lead to osteoarthritis-like pathological changes in rat knees, with increased expression of MMP3, MMP13, and ADAMTS4 in knee cartilage and decreased expression of BMAL1." (PMID 39010104, 2024). "On the other hand, MMP-13, also named collagenase-3, a member of the MMP family of neutral endopeptidases, is highly overexpressed in hypertrophic chondrocytes and synovial cells in osteoarthritis." (PMID 37189729, 2023).
osteoarthritis (continued). "Studies have shown that Mg2+ may affect osteoarthritis by inhibiting the expression of IL-1β, TNF-α, MMP13, and ADAMTS5 genes in macrophages, synoviocytes, and chondrocytes." (PMID 36546928, 2022). "Human osteoarthritis chondrocytes can be inhibited by senegenin by inhibiting PI3K/AKT/NF-κB signaling pathway, inhibiting the expression of MMP-1, MMP-3, and MMP-13 induced by IL-1β, and the production of NO and PGE2 was reduced in human osteoarthritis chondrocytes." (PMID 35924058, 2022). "Percentages of ColX+ and MMP13+ chondrocytes more than doubled in DMM mice compared with sham mice, and iPTH significantly reduced the magnitude of increase, indicating that iPTH inhibited chondrocyte degeneration in osteoarthritis." (PMID 33646122, 2021). "Aggrecan, Col-10, MMP-13, SOX6, and Runx2 are closely related to osteoarthritis." (PMID 34926690, 2021). "The changes in expression of the DEGs listed in the osteoarthritis pathway included strong down-regulation of cartilage matrix molecules (COL2A1, MATN3, and ACAN) and up-regulation of matrix proteases (ADAMTS5 and MMP13) and apoptosis-related molecules (CASP4)." (PMID 32294904, 2020). "The high expression of TIMP-1, MMP-1 and MMP-13 in the cartilage may be responsible for the degeneration, and PCL rupture may trigger meniscus degradation and ultimately osteoarthritis." (PMID 30626725, 2019). "Development of enthesopathies may be mediated by matrix metalloproteinase 13 (MMP13), a gene that prepares cartilage matrix for calcification and a critical target gene during the progression of osteoarthritis." (PMID 30808384, 2019). "The purpose of this study was to investigate the influence of moderate physical activity (MPA) on the expression of osteoarthritis (OA)-related (IL-1β, IL-6, TNF-α, MMP-13) and anti-inflammatory and chondroprotective (IL-4, IL-10, lubricin) biomarkers in the synovium of an OA-induced rat model." (PMID 30691048, 2019). "Knee loading (0.5–3 N for 5 min) was applied to the right knee of surgically-induced osteoarthritis (OA) mice as well as normal (non-OA) mice, and MMP13 activity in the femoral cartilage was examined." (PMID 24180431, 2013). "MMP-13, a zinc dependent protease which catalyses the cleavage of type II collagen, is expressed in osteoarthritis (OA) and rheumatoid arthritis (RA) patients, but not in normal adult tissues." (PMID 20824169, 2010). "MMP-13 and IGFBP-5 are important factors involved in osteoarthritis (OA)." (PMID 19948051, 2009). "In human osteoarthritis chondrocytes, ET-1 controls the production of MMP-1 and MMP-13." (PMID 15743480, 2005). "The genes enriched in the osteoarthritis pathway revealed by IPA of the DEGs in the palovarotene-treated chondrocytes included various matrix catabolic genes (Adamts4, Adamts5, Mmp9, Mmp10, Mmp12, and Mmp13) and cell death-related genes (Casp1, Casp3, and Casp6)." (PMID 39062860, 2024). "When administered intra-articularly to rats with osteoarthritis, these hybrid CAP-exosomes (hybrid CAP-Exo/CRISPR/Cas9 sgMMP–13) penetrated deep into the cartilage matrix, delivered the plasmid to chondrocytes, and knocked down the expression of matrix metalloproteinase 13 (MMP–13)." (PMID 39339233, 2024). "Likewise, in pathological conditions such as osteoarthritis (OA), in which articular chondrocytes develop a hypertrophic phenotype, the upregulation of Runx2 and ALP has been detected, along with Type X collagen, MMP13 and IHH and reduced Type II." (PMID 39791725, 2024). "Similarly, in our study, we observed increased MMP13 expression and decreased levels of aggrecan and collagen II, the main components of the extracellular matrix, indicating ongoing cartilage damage in MIA-induced osteoarthritis." (PMID 38045809, 2023).
osteoarthritis (continued). "Percentages of COL X+ and MMP13+ chondrocytes in DMM mice were more than twice those in the sham controls, and celecoxib dramatically reduced the magnitude of increase, which indicates that inhibiting the increase in PGE2 attenuates articular cartilage and chondrocyte degeneration in osteoarthritis." (PMID 36078169, 2022). "HIF-2α is involved in a pathway that promotes osteoarthritis degradation and regulates the expression of genes related to chondrocyte hypertrophy and differentiation, such as COL10A1 and RUNX2, and the expression of genes related to ECM degradation, such as MMP9, MMP13, MMP3, ADAMTS." (PMID 36503684, 2022). "Importantly, our study revealed that FA suppressed MMP‐1, MMP‐3, and MMP‐13 production stimulated by IL‐1β in vitro, suggesting that FA may be effective for restoring ECM composition and structure to halt osteoarthritis progression." (PMID 34078001, 2021). "Similarly, MMP-13, MMP-3, MMP-2, and MMP-9 increased in the cell line model of osteoarthritis." (PMID 32189997, 2020). "Since osteoarthritis increases S100-A4 expression and MMP13 expression, we suggest that the lack of Y-27632-induced S100-A4 levels under hypoxic conditions may beneficially decrease the risk of MMP13 -mediated degradation of extracellular matrix." (PMID 28623370, 2017). "It is argued that hypertrophy is also a feature of osteoarthritis (OA) because the permanent chondrocytes of articular cartilage can express markers of hypertrophic endochondral chondrocytes, such as collagen X (COL10A1) and matrix metalloproteinase 13 (MMP13) during degeneration." (PMID 23965235, 2013). "However, in our equine MSC model, at the mRNA and the protein level, type X collagen, the main marker of hypertrophy and osteoarthritis, was not expressed or only weakly expressed, as was Mmp13, the main protease involved in cartilage degradation upregulated in late hypertrophic chondrocytes." (PMID 29439436, 2018).
breast carcinoma (153 papers, 2004 to 2025). "MMP13 is associated with bone metastasis and osteolytic processes in breast cancer, indicating its potential as a therapeutic target." (PMID 41017855, 2025). "A high level of MMP-13 expression was not only detected in primary breast cancers but also in metastatic lymph nodes that are associated with cancer aggressiveness." (PMID 35805035, 2022). "MMP-13 is associated with breast cancer-induced osteolysis, suggesting that MMP-13 is a promising therapeutic target for breast cancer bone metastasis." (PMID 36741729, 2022). "Previous studies have shown that inhibition of MMP13 activity causes inhibition of the growth of the breast cancer cell lines MDA-MB-231 and 4T1.2." (PMID 36106139, 2022). "Elevated levels of MMP13 have been associated with decreased overall survival and increased lymph node metastasis in breast cancer." (PMID 34452576, 2021). "MMP13 expression is associated with increased breast cancer cell growth, EMT, migration and invasion." (PMID 34643237, 2021). "Overexpression of MMP13 in tumors is associated with aggressive tumor phenotype in breast cancer patients." (PMID 34643237, 2021). "With both methods we identified up-regulated matrix metalloproteinases (such as MMP11 and MMP13) which are a class of enzyme known to be involved in cancer invasion and metastasis and have been linked to breast cancer outcomes." (PMID 30835723, 2019). "These are relevant findings, considering that MMP13 is overexpressed in a variety of malignant tumors, such as in breast carcinomas, and is implicated in bone metastasis in breast cancer." (PMID 29996935, 2018). "It is possible down regulation of MMP13 was also the cause of RKIP inhibition of local breast cancer cells invasion in vivo." (PMID 26308852, 2015). "Our MMP13 expression rescue experiments indeed demonstrated the causal role of MMP13 in RKIP-mediated regulation of breast cancer cells invasion in vitro." (PMID 26308852, 2015). "MMP13 was identified as a part of the breast cancer metastasis signature and was associated with decreased overall survival and metastasis in breast cancer and renal cell carcinoma." (PMID 25880591, 2015). "Among them, a higher immunoexpression of MMP13 (collagenase 3) in stromal cells was associated with positive nodes in breast cancer." (PMID 24229053, 2013). "Previously we have shown that MMP13, while barely detectable in naïve mammary fat pads, was abundantly expressed in the tumor-associated murine stroma of breast cancer cell line and primary tumor xenografts." (PMID 22253746, 2012). "We have previously shown that MMP13 was dramatically induced in the tumor-associated stroma of human breast cancer xenografts." (PMID 22253746, 2012). "This study aimed at evaluating plasma levels of MMP1, MMP8 and MMP13 as diagnostic and prognostic markers of breast cancer." (PMID 18366705, 2008). "In this study, we evaluated the usefulness of circulating MMP1, MMP8 and MMP13 levels as diagnostic and prognostic markers in breast cancer." (PMID 18366705, 2008). "The upregulation of MMP13 has been linked to a poor prognosis in breast cancer patients." (PMID 40004168, 2025). "Tumor-derived MMP13 is associated with an aggressive tumor phenotype in breast cancer patients." (PMID 33287358, 2020). "MMP-11 and MMP13 expression were also promising markers linked to the poor outcome of breast cancer which may be a novel target for the treatment of breast cancer." (PMID 31398937, 2019). "Also of note was the significant decrease in VCAM1 (2.6-fold), TBS2 (5.2-fold), MMP1 (7.7-fold), COL14A1 (2-fold), and MMP13 (3.3-fold), all of which have been associated with breast cancer cell invasion and metastasis to bone, lung, and/or the lymphatics." (PMID 29735912, 2018). "MMP13 is a part of the breast cancer metastasis signature and tumor cell expression of MMP13 is linked with increased invasiveness and ability to metastasize in melanoma and breast cancer." (PMID 25880591, 2015).